MIR323B (microRNA 323b)
Synonyms: hsa-mir-323b; hsa-mir-453; MIR453; MIRN453; mir-323b
Gene: MicroRNA gene on chromosome 14 (101,056,219 to 101,056,300, forward strand). Ensembl gene ENSG00000208004.
Gene Ontology:
Biological process: miRNA-mediated post-transcriptional gene silencing
Cellular component: RISC complex
Homologues: Orthologues: chimpanzee MIR323B (100% identical), macaque MIR323B (100% identical). Paralogues in human: MIR323A (80% identical), MIR496 (70% identical), MIR410 (68% identical), MIR154 (67% identical), MIR409 (67% identical), MIR494 (66% identical), MIR539 (61% identical), MIR656 (61% identical), MIR1185-1 (60% identical), MIR487A (60% identical), MIR487B (60% identical), MIR382 (59% identical), and 4 more.